RHOA (ras homolog family member A)
Diseases named in the same sentence as RHOA in open-access papers (continued):
Sharing a sentence is not in itself a finding about the gene and the disease.
cancer (continued). "The actin and microtubule cytoskeleton dysregulation is responsible for cellular transformation and migration found in many cancers and activation and deactivation of Rho-GTPase family proteins majorly regulates actin filaments through Ras homolog gene family, member A (RHOA) signaling." (PMID 29254242, 2017). "RhoA has been suggested to modulate the cell cycle and survival of cancer cells." (PMID 28254846, 2017). "Likewise, elevated RhoA expression was found to correspond to poor prognosis and high recurrence rates in particular cancers." (PMID 28184030, 2017). "Thus, advanced carcinoma cells require elevated RhoA activity for establishing robust junctions, which triggers tension-sensitive reorganization of actin/adhesion regulators." (PMID 29184140, 2017). "Thus, a subgroup of carcinoma cells gained the property to require extra RhoA signals for junction formation." (PMID 29184140, 2017). "In contrast, when the expression of TAp63 is decreased in cancer cells, miR-133b expression is downregulated, and RhoA expression is increased, ultimately inhibiting the PI3K/Akt pathway, thus promoting TAp63 expression and TAp63-related apoptosis and inhibiting TAp63-related proliferation." (PMID 27894087, 2016). "Among these, RAC1 and RHOA are already present in the Cancer Gene Census, adding confidence to the hypothesis that also RHOF might play a role in cancer." (PMID 26860319, 2016). "RhoA is a key player in many different types of cancer cells." (PMID 26828592, 2016). "Along with canonical TGF-β signaling through Smad-dependent transcriptional regulation, Crk-dependent EMT though Rac1 and RhoA activation may play a role in cancer progression." (PMID 27027347, 2016). "To evaluate if the activation of the small GTPase RhoA has a role in the response to γ-radiation in cancer cells, we generated stable clones of HeLa cells expressing either the constitutively active HeLa-RhoA-V14 or the dominant negative HeLa-RhoA-N19 RhoA mutants." (PMID 26649141, 2016). "In the present study, we found that decreased GTP-RhoA and increased cAMP in CMSP-treated cells, indicated that cAMP- induced RhoA activation blockade might be a key factor affected by CMSP regulating the differentiation of cancer cells." (PMID 27501997, 2016). "Based on RHOA's involvement in other cancers, in this study, we herein investigated whether RHOA inhibitors could successfully be identified as an evidence-based, biomarker-driven therapeutic option for GC patients." (PMID 27806312, 2016). "Overall, our data support the existence of a “cross talk” between RhoA signaling and DNA damage response and repair pathways in cancer cells, which may contribute to increased radioresistance." (PMID 26649141, 2016). "Ubiquitylation of Rac1, RhoA and Cdc42 can be deregulated in cancer cell lines, a fact that could indicate a link between Rho GTPase protein ubiquitylation and cancer." (PMID 27104658, 2016). "Consequently, rounded-amoeboid cancer cells with high levels of RhoA or ROCK-driven actomyosin contractility are more efficient during transendothelial migration than elongated cells bothin vitro andin vivo." (PMID 27158478, 2016). "RhoA/ROCK1 is known as a downstream pathway of RhoGDIα in many cancers." (PMID 27557508, 2016). "Lipin-1 depletion also decreased cancer cell migration through RhoA activation." (PMID 25834103, 2015). "We previously reported that RhoA depletion reduces cancer cell adhesion to ECs and delays cancer cell intercalation; however, RhoA depletion reduced cancer cell velocity on top of ECs before intercalation, which was not the case when RhoC or ROCKs were depleted." (PMID 25677806, 2015).
cancer (continued). "This is consistent with recent studies that ERRα can down regulate RHOA stability or induce WNT11 expression to increase cancer cell migration, while knockdown of ERRα during the early stages of zebrafish embryonic development results in inhibition of cell migration." (PMID 26160845, 2015). "The setup of our proteomic screen and the effects of PKCα activity on amoeboid cancer cells suggest that PKCα might activate the small GTPase RhoA or ROCK kinase." (PMID 25924946, 2015). "Rnd3 seems to regulate cancer cell invasion mainly through its effects on RhoA/ROCK activity." (PMID 25705175, 2015). "Last, our study suggests that targeting ROCK signaling, which is a shared downstream mediator of both RhoA and RhoC, may be sufficient to block K-Ras-driven cancer as has been previously suggested." (PMID 26030593, 2015). "The invasive activity of cancer cells overexpressing ErbB-2 is mediated by Plexin-B1 and RhoA." (PMID 25137062, 2014). "For example, high c-Myc suppresses cancer metastasis, most likely through the direct transcriptional repression of integrin subunits, and cyclin A2 negatively controls cell motility by promoting RhoA activation and cytoskeletal rearrangements." (PMID 25360999, 2014). "In response to extracellular ligand binding, integrins undergo a conformational change that permits the recruitment of cytoplasmic adaptor proteins and signaling molecules, including small Rho GTPases, Cdc42, Rac1 and RhoA, which are key players in cell migration and cancer metastasis." (PMID 25149533, 2014). "This strategy may be beneficial not only in cancers where DGKζ is overexpressed, but possibly also in cases where DGKζ is expressed at normal levels but Rac1 or RhoA are overexpressed or hyperactive." (PMID 24646293, 2014). "RhoA and RhoC have reciprocal roles in controlling cancer cell motility." (PMID 24224016, 2013). "The expression of RhoA and RhoC is frequently induced in human cancers." (PMID 23382905, 2013). "The PKCε-RhoA signaling module was shown to modulate cancer cell invasion and motility." (PMID 24191200, 2013). "Hence, by secreting CTHRC1 into its microenviroment, cancer cells stimulate their own motility and that of adjacent cancer cells by activating RhoA signaling." (PMID 23922981, 2013). "Knocking down of RhoGDI1 can promote cancer cell metastasis via inducing RhoA activation." (PMID 23538840, 2013). "Our data that FLCN-deficient cells have low levels of RhoA and ROCK activity are consistent with the known role of p0071 as a positive regulator of RhoA, but surprising given that RhoA is often activated in human cancer." (PMID 23139756, 2012). "RhoA has been recently found in the nucleus of cancer cells and upon DNA damage, suggesting that oxidative stress could cause the translocation of RhoA into the nucleus." (PMID 23209630, 2012). "RhoA has been shown to control cancer metastasis and progression." (PMID 22235332, 2012). "Given the phenotypes of cell shape changes and the retraction of cellular protrusions that are characteristic of RhoA activation, we investigated whether RhoA signaling is altered by Cuc IIa treatments in cancer cells." (PMID 21304528, 2011). "Basal level RhoA activity is essential for the invasion and metastasis of cancer cells." (PMID 20082722, 2010). "In HCT116 cells, the multiple shRNAs expression constructs could efficiently and simultaneously induce inhibition of RhoA and RhoC genes and markedly inhibit the invasion and migration potentials of cancer cells." (PMID 19374769, 2009). "Recent accumulating evidences have shown that RhoA and RhoC are over-expressed in many kinds of cancers, and they may play important roles in initiation and progression of cancers." (PMID 19374769, 2009). "In human cancers, the alteration of RhoA expression is involved in tumorigenesis." (PMID 18651974, 2008). "Indeed, overexpression of RhoA was detected in several types of cancer including bladder, testicular, ovarian, colon, breast, and lung." (PMID 18651974, 2008).
cancer (continued). "This may be due to a previous report which found that NO decreased RhoA activity, which is a well-known activator of cancer cell motility." (PMID 19025611, 2008). "Since the small GTPase RhoA requires geranylgeranylation to promote cancer invasion, we suggested that RhoA could represent a potential candidate to mediate ZOL effects." (PMID 12771933, 2003). "Notably, MMP14 is targeted to invadopodia in invasive cancer cells via RhoA-dependent exocytosis." (PMID 40705412, 2025). "This study suggested that the upregulation of Slit2 might contribute to mechanical allodynia after carcinoma implantation, likely by enhancing excitatory synapse formation through the suppression of Robo1 and subsequent removal of the RhoA-mediated inhibition of neurite outgrowth." (PMID 40249935, 2025). "Therefore, we reasonably speculate that ARHGEF10L may be involved in various cancer occurrences through RhoA/Rho kinase signaling pathway." (PMID 38180276, 2024). "Therefore, we then focused to explore whether the increased RhoA activity because of the p190RhoGAP silencing in cancer cells contributes to decreased ATX expression." (PMID 38182748, 2024). "Simvastatin might also reduce cancer metastasis by suppressing the RhoA pathway." (PMID 37298689, 2023). "Therefore, treatment with a ROCK inhibitor may significantly decrease the invasion area and the number of invaded cancer cells owing to podoplanin overexpression-dependent enhancement of RhoA activity in CAFs." (PMID 36376711, 2023). "One stage II (pT4N0) MMR-proficient cancer (with the Gly17Glu mutation of the RHOA gene) occurred in the nonampullary duodenum of a 50-year-old man, while the other one, a stage III (pT3N1) MMR-proficient SBA (with the Tyr42Cys mutation), was found in the ileum of a 52-year-old female patient." (PMID 36812376, 2023). "As EGF receptor, Vav1, RhoA, Rac1, and BPGAP1 are all associated with oncogenesis and/or cancer metastasis, the identification of this novel EGFR-BPGAP1-Vav1-Rac1-RhoA signaling axis could provide new approaches to a combinatorial therapeutic intervention in cancer progression." (PMID 36598812, 2023). "Furthermore, activated Src was shown to modulate Rac1 and RhoA signaling in migrating cancer cells." (PMID 35563773, 2022). "Importantly, inhibition of RhoA-SRF-MRTFA pathway by CCG-1423 reversed Nogo-B-induced cancer progression, demonstrating that CCG-1423 may be a potential target drug of NPC." (PMID 35075114, 2022). "The exact mechanism for this cancer development is still not well understood, but it might be due to the ability of RhoH to regulate the activities of other cancer-related small Rho GTPases, including RhoA, Cdc42, Rac1 and RhoF." (PMID 33923951, 2021). "Thus, low levels of RhoH resulting from aSHM might directly or indirectly promote Rac1-, RhoA- or Cdc42-induced cell division and migration, leading to an increase in cancer progression." (PMID 33923951, 2021). "Additionally, a modified EGFP/mRFP Raichu-RhoA biosensor successfully observed the up-regulation of RhoA activity, which is related to numerous cellular activities and is known to drive cell motility in invasive cancers." (PMID 34138374, 2021). "In addition, previous studies have proven that mediation of RhoA regulates proliferation and differentiation of mesenchymal stem cells, adipose-derived stem cells (ADSCs), muscle stem cells, and a bulk of cancer cells." (PMID 32508931, 2020). "The stiffening response of endothelial cells in response to force applied by magnetic tweezers requires active RhoA and cytoskeletal remodelling has been associated with GPER in human dermal fibroblasts, suggesting that GPER may modulate mechanosensing through RhoA in cancer cells." (PMID 31991740, 2020). "Therefore, the status of oxidative stress might be a therapeutic strategy for the inhibition of RhoA in cancer cells and indirectly influence cancer cell EMT." (PMID 33383973, 2020).
cancer (continued). "Therefore, we speculated that BTBD9 regulated the degradation of TNFAIP1 and affected the metastasis of cancer cells in a RhoA-independent manner." (PMID 32327643, 2020). "Thus, we speculate that RHOA may serve as a particularly feasible molecular target for the treatment of malignant tumors." (PMID 31820783, 2020). "Thus, opposite to the tumor-suppressive roles of DGKγ DGKζ may also promote tumorigenesis by potentiating cell invasion and migration in several cancer types by regulating Rac1 and RhoA activity." (PMID 32722576, 2020). "Therefore, it is of interest to investigate whether BNIP-2 can scaffold microtubule-regulated GEF-H1 and RhoA for RhoA-mediated cancer cell migration." (PMID 32789168, 2020). "In conclusion, the present results suggest that the EPHB6 mutation promotes cancer cell proliferation and migration/invasion and induces CAM-DR, and these effects are mediated by the stabilization of EPHA2 and the activation of downstream JNK/CDH11/RhoA/FAK signaling." (PMID 31160603, 2019). "By establishing a positive feedback loop resulting in hyperactivation of RhoA, membrane tension could act as a mechanical signal that allows cells to move rapidly with high directional persistence into fibrotic areas (e.g., wounds) or promote cancer invasion." (PMID 31607653, 2019). "Thus, it has been found that abnormalities in RhoA function could lead to cancer progression through metastatic growth." (PMID 30779783, 2019). "Furthermore, ARHGAP5 can also facilitate cancer development independent on RhoA activation." (PMID 31097692, 2019). "Therefore, new strategies should be carried out to inhibit RhoA in cancer cells." (PMID 30884855, 2019). "Thus, Ran-RhoA signaling complex may be an effective molecular target for controlling cancer metastasis." (PMID 31209254, 2019). "Moreover, blocking Shh signaling, increasing the amount of RhoA-GTP, inhibiting the interaction between RhoA and Rho-GDI, inducing the activation of AMPK and p38 MAPK are suggested to be implicated in anti-cancer effects of simvastatin." (PMID 31557936, 2019). "In this study, we showed that the combination of biomarkers demonstrated a better prognostic value than either one of Pin1, RhoA or RhoC, suggesting that these factors act together in the cancer metastatic process and thus effect of downregulation of one factor could be compensated by the others." (PMID 31324164, 2019). "Therefore, in parallel to IGF-1, TGF-β could contribute to the RhoA-dependent enhancement of cancer cell invasiveness via PAI-1." (PMID 29535813, 2018). "Notably, while these studies used GTPase‐deficient G14V or Q63L in RhoA and G12V or Q61L Rac1 analogous to oncogenic Ras mutations, such mutations in Rho GTPases have not been detected in clinical cancer." (PMID 29749605, 2018). "Upon contact with the Eph receptor bearing cell, ephrinB1 expressed at the surface of the cancer cell may enhance RhoA activation by engaging RhoGDI, thus removing this negative regulator from RhoA, and leading to migration and invasion of the host cancer cells." (PMID 29059157, 2018). "Once we established that in an exogenous expression system EphB2-Fc promotes the activation of RhoA and cell migration as well as cell invasion through an ephrinB1/RhoGDI1 interaction, we next assessed whether depletion of endogenous ephrinB1 or RhoA influences cancer cell migration and invasion." (PMID 29059157, 2018). "ROCK1 is the key mediator of RhoA activity, and is a multifunctional member of the AGC (protein kinase A/G/C) kinase family that has also been implicated in the modulation of stress fiber assembly, cell contraction, apoptosis, migration, and invasion of multiple cancer cell types." (PMID 28841710, 2017). "Therefore, C5a produced by both cancer cells and cleavage of serum C5 in the cancer microenvironment may continuously stimulate the conversion of RhoA-GDP to RhoA-GTP by stimulating C5aR, resulting in increased cancer cell motility and invasion." (PMID 27756879, 2016).
cancer (continued). "Furthermore, our previous and others’ studies indicated the inhibition of ERRα can also suppress the migration and invasion of cancer cells via suppression the epithelial-to-mesenchymal transition, down regulation the stability of RHOA or induction the expression of WNT11." (PMID 26871469, 2016). "As with Rac1, no mutations in RhoA had been detected in human cancers until very recently." (PMID 27104658, 2016). "There are 3 Rho isoforms but little evidence of Rho isoform-specific effectors, so the mechanisms by which the isoforms exert differential effects are unknown, but RhoA and C tend to exhibit oncogenic effects in a number of cancers whereas RhoB suppresses tumourigenesis." (PMID 27487152, 2016). "Similarly, RhoA knockdown inhibits the migration of cancer cells." (PMID 26510742, 2016). "Moreover, the viral perturbation of host cellular networks reflected disease etiology in that host genes (e.g. CTCF, RHOA, and CDKN1B) identified were frequently essential and significantly associated with Mendelian and orphan diseases, or somatic mutations in cancer." (PMID 27632082, 2016). "Indeed, measurements of cancer driver pathway activation, such as Src,8 RhoA 9 and Rac,7 have recently been reported using in vivo FLIM imaging of FRET (Fluorescence Resonance Energy Transfer) biosensors, and others have shown that multi-modal CARS 2-photon imaging can be combined with FLIM." (PMID 28243514, 2015). "We now show that depolymerization of the actin cytoskeleton of cancer cells with cytochalasin D (Cyt D) induces nuclear-cytoplasmic translocation of EMT-associated transcription factors, increased E-cadherin expression, reduced cell shape and size and reduced activation of RhoA." (PMID 25756282, 2015). "While we focused mostly on the use of a modified MYXV we were able to show that the effects of F11 on MYXV growth in cancer cells could be mimicked through the use of pharmacological inhibition or siRNA-mediated silencing of key regulators of cortical actin (RhoA, RhoC, mDia1, or LIMK2)." (PMID 24391902, 2013). "However, RhoA mRNA expression was similar in ccRCC and non-cancer tissues." (PMID 21119662, 2011). "Different hypotheses regarding RHOA role in these cancers are being explored." (PMID 20236512, 2010). "Moreover, some reports showed that down-regulating the expression of RhoA and RhoC using small interfering RNA (siRNA) approaches may inhibit the proliferation and invasiveness of cancer cells." (PMID 20828398, 2010). "Both pharmacological inhibition with Box5 and genetic ablation of RHOA effectively abrogated GNG10-induced oncogenic phenotypes and the upregulation of cancer stem cell markers (CD44, CD133, OCT4, Nanog, SOX2)." (PMID 42252561, 2026). "This MALL-SDC4 program promotes RhoA/phosphorylated myosin light chain 2 (p-MLC2)-dependent amoeboid motility and sensitizes cancer cells to Schwann cell-derived pleiotrophin, strengthening directed neural invasion." (PMID 42017444, 2026). "In cancer models, CLDN18 dysregulation alters cytoskeletal dynamics and activates signalling cascades involving RhoA/ROCK and β-catenin, which modulate cell adhesion, migration, and inflammatory gene expression." (PMID 41226477, 2025). "It has been reported that the RhoA/ROCK pathway upregulates YAP1 transcriptional activity, which mediates cancer invasion." (PMID 40388100, 2025). "In the cancer cell line LS513, RhoA levels increased from 0.6 pg mL−1 before stretching to 1.4 pg mL−1 after stretching." (PMID 39887960, 2025). "Hypoxia-derived exosome circR-133 is transported to normal cancer cells and promotes cell migration through the miR-133a/GEF-H1/RhoA axis." (PMID 39744442, 2025). "This study investigates the expression patterns of RhoA and Rac1 under mechanical strain in post‐surgical CRC clinical samples to elucidate their roles in cancer progression and identify therapeutic targets." (PMID 39887960, 2025).